CCDC85A (coiled-coil domain containing 85A)
Description:
May play a role in cell-cell adhesion and epithelium development through its interaction with proteins of the beta-catenin family.
Synonyms: KIAA1912
Tractability: PROTAC: its protein half-life has been measured.
Gene: Protein-coding gene on chromosome 2 (56,183,751 to 56,386,178, forward strand). Ensembl gene ENSG00000055813.
Subcellular location: Cell junction, adherens junction
Gene Ontology:
Molecular function: protein binding
Cellular component: adherens junction
Genetic constraint (gnomAD): Loss-of-function variants: 35 observed, 43.85 expected, observed/expected ratio (o/e) 0.8, 90% interval 0.61 to 1.06. The synonymous counts are far from expectation, so gnomAD's model fits this gene poorly and the ratio says little. Missense variants: 784 observed, 693.42 expected, observed/expected ratio (o/e) 1.13, 90% interval 1.07 to 1.2. Synonymous variants: 349 observed, 281.75 expected, observed/expected ratio (o/e) 1.24, 90% interval 1.13 to 1.35.
Homologues: Orthologues: chimpanzee CCDC85A (99% identical), macaque CCDC85A (95% identical), dog CCDC85A (93% identical), pig CCDC85A (93% identical), guinea pig CCDC85A (93% identical), rat Ccdc85a (92% identical), mouse Ccdc85a (91% identical), rabbit CCDC85A (81% identical), tropical clawed frog ccdc85a (55% identical), zebrafish ccdc85a (42% identical), zebrafish ccdc85al (40% identical), Caenorhabditis elegans picc-1 (22% identical). Paralogues in human: CCDC85C (34% identical), CCDC85B (16% identical).
Diseases named in the same sentence as CCDC85A in open-access papers:
CCDC85A is named in the same sentence as 20 diseases in open-access papers, as found by Europe PMC text mining. Sharing a sentence is not in itself a finding about the gene and the disease. The quoted sentences say what the papers report.
epilepsy (2 papers, 2023). A brain disorder characterized by episodes of abnormally increased neuronal discharge resulting in transient episodes of sensory or motor neurological dysfunction, or psychic dysfunction. "Little is also known about the potential role of CCDC85A in epilepsy pathogenesis, and few functional studies have been conducted (PS3/BS3)." (PMID 36899667, 2023). "Further, FUMA analysis identified six overlapping genes, including SMEK2, PNPT1, EFEMP1, CCDC85A, VRK2, and BCL11A, shared between COVID-19 and epilepsy." (PMID 37781245, 2023). "Of these, 6 genes were found to be shared between COVID-19 and epilepsy, including SMEK2, PNPT1, EFEMP1, CCDC85A, VRK2, and BCL11A, all located on chromosome 2." (PMID 37781245, 2023). "While little is known about the potential roles of CCDC85A and SPAST in epilepsy pathogenesis and few functional studies have been conducted, they remain interesting candidate genes." (PMID 36899667, 2023).
Alzheimer disease (1 paper, 2022). A progressive, neurodegenerative disease characterized by loss of function and death of nerve cells in several areas of the brain leading to loss of cognitive function such as memory and language. "In the early stage of Alzheimer’s disease, the upregulation of Ccdc85a expression may be a compensation for the increase in amyloid β-protein and the elimination of amyloid β-protein metabolism." (PMID 35309141, 2022).
gastric cancer (1 paper, 2023). A primary or metastatic malignant neoplasm involving the stomach. "High expression of CCDC85A was detected in HSC43 (scirrhous gastric cancer), Capan1 (pancreatic ductal adenocarcinoma), and U87MG (glioblastoma) cells." (PMID 37534255, 2023).
pancreatic carcinomas (1 paper, 2023). "Immunohistological analysis revealed that CCDC85A is expressed to varying degrees by cancer cells and CAFs in gastric and pancreatic carcinomas." (PMID 37534255, 2023). "To confirm CCDC85A expression in tumors, we performed immunohistochemical analysis of several cases of gastric and pancreatic cancer." (PMID 37534255, 2023). "Our results suggest that tumors showing high expression of CCDC85A (e.g., gastric and pancreatic cancer) may be refractory to ER stress; therefore, treatments such as CDDP, which induce ER stress, are less effective than they are against CCDC85A-negative tumors." (PMID 37534255, 2023).
thyroid cancer (1 paper, 2023). "By contrast, high expression of CCDC85A mRNA was detected in around 6% of cancers, and higher incidence of CCDC85A expression was observed in some other cancers, e.g. thyroid cancer." (PMID 37534255, 2023).
cancer (1 paper, 2023). A tumor composed of atypical neoplastic, often pleomorphic cells that invade other tissues. "NFs secreted exosomes containing miR-224-3p, which affected expression of CCDC85A by cancer cells and ameliorated tumor resistance to cisplatin." (PMID 37534255, 2023). "Downregulation of CCDC85A in cancer cells revealed that these cells are vulnerable to endoplasmic reticulum (ER) stress induced by thapsigargin or tunicamycin, which were ameliorated after addback of CCDC85A." (PMID 37534255, 2023). "We found that CCDC85A associated with GRP78 and GRP94, which activates PERK by interfering with the binding of GRP78 and GRP94 to PERK, leading to ER stress resistance of CCDC85A-expressing cancer cells." (PMID 37534255, 2023). "Because CCDC85A was expressed not only in CAFs but also in some cancer cells, we examined CCDC85A expression in various human cancer cell lines." (PMID 37534255, 2023). "CCDC85A was detected in both CAFs and cancer cells to varying degrees, but rarely in normal gastric mucosa or in normal pancreas secretory ducts." (PMID 37534255, 2023). "Taken together, these results indicate that CCDC85A prevents apoptosis of cancer cells due to ER stress, thereby increasing resistance to CDDP." (PMID 37534255, 2023). "The data suggest that miR-224 and CCDC85A are promising targets for preventing resistance of cancer cells to drugs that trigger ER stress." (PMID 37534255, 2023). "Pancancer analysis of miR-224-3p and CCDC85A expression in the TCGA dataset using cBioportal revealed that deletion of miR-224-3p occurred in around 5.6% of cancers." (PMID 37534255, 2023). "To examine the effect of CCDC85A on cancer cells, we targeted the CCDC85A gene in Capan1 cells." (PMID 37534255, 2023). "Because CCDC85A upregulated TGFβ in cancer cells under the hypoxic conditions, it may promote EMT and activate Rac1/CDC42." (PMID 37534255, 2023). "Future studies should try to evaluate both CCDC85A protein and miR-224-3p levels in cancer cells and stromal cells from various tumor specimens to generalize our conclusions, although an inverse relationship between CCDC85A protein and miR-224-3p was observed at least in some cancer cell lines." (PMID 37534255, 2023). "However, we cannot rule out at present the possibility that CCDC85A expression of cancer cells is not regulated exclusively by miRNA of fibroblasts, because in some tumor specimens, CCDC85A was stained in cancer cells but not in stromal fibroblasts." (PMID 37534255, 2023). "Although the signaling pathway is not clear, CCDC85A promoted EMT, which activates Rac1/CDC42 in various cancer cells." (PMID 37534255, 2023).
tumor (1 paper, 2023). "To investigate the effects of miR-224-3p on the tumor environment, we focused on the coiled-coil domain containing 85A (CCDC85A) as a target gene of miR-224-3p." (PMID 37534255, 2023).
CCDC85A also shares sentences with these, for which no sentence is quoted: amyotrophic lateral sclerosis (1 paper); attention deficit-hyperactivity disorder (1); autism spectrum disorder (1); bipolar disorder (1); cervical cancer (1); COVID-19 (1); eating disorder (1); glioblastoma (1); Hydrocephalus (1); major depressive disorder (1); mental disorder (1); pancreatic ductal adenocarcinoma (1); schizophrenia (1).